FKBP3 (FKBP prolyl isomerase 3)
Description:
FK506- and rapamycin-binding proteins (FKBPs) constitute a family of receptors for the two immunosuppressants which inhibit T-cell proliferation by arresting two distinct cytoplasmic signal transmission pathways. PPIases accelerate the folding of proteins.
Synonyms: FKBP-25; FKBP-3; FKBP25; PPIase
Tractability: Small molecule: a structure with a bound ligand is known; it belongs to a druggable protein family. PROTAC: ubiquitination databases record sites on it; its protein half-life has been measured; a small molecule that binds it is known.
Target class: Isomerase; Enzyme
Gene: Protein-coding gene on chromosome 14 (45,115,599 to 45,135,319, reverse strand). Ensembl gene ENSG00000100442.
Subcellular location: Nucleus
Subcellular location (Human Protein Atlas): Cytosol
Gene Ontology:
Molecular function: protein binding; RNA binding; FK506 binding; signaling receptor activity; peptidyl-prolyl cis-trans isomerase activity
Cellular component: cytosol; nucleus
Genetic constraint (gnomAD): Loss-of-function variants: 10 observed, 17.73 expected, observed/expected ratio (o/e) 0.56, 90% interval 0.35 to 0.96. The upper end of that interval is the gene's LOEUF score, 0.96, which puts it in group 4 of 6, group 1 being the genes least tolerant of losing a copy. Missense variants: 176 observed, 164.09 expected, observed/expected ratio (o/e) 1.07, 90% interval 0.95 to 1.22. Synonymous variants: 58 observed, 59.96 expected, observed/expected ratio (o/e) 0.97, 90% interval 0.78 to 1.2.
Homologues: Orthologues: chimpanzee FKBP3 (100% identical), dog FKBP3 (97% identical), guinea pig FKBP3 (97% identical), pig FKBP3 (97% identical), mouse Fkbp3 (94% identical), rat Fkbp3 (89% identical), macaque FKBP3 (85% identical), tropical clawed frog fkbp3 (80% identical), zebrafish fkbp3 (56% identical), Drosophila melanogaster zda (28% identical), Caenorhabditis elegans fkb-4 (22% identical), Caenorhabditis elegans fkb-5 (22% identical). Paralogues in human: FKBP9 (30% identical), FKBP10 (30% identical), FKBP15 (25% identical), FKBP4 (22% identical), FKBP2 (22% identical), FKBP5 (22% identical), FKBP1A (21% identical), FKBP1C (21% identical), FKBP1B (21% identical), FKBP7 (21% identical), FKBP11 (20% identical), FKBP14 (19% identical), and 6 more.
Diseases named in the same sentence as FKBP3 in open-access papers:
FKBP3 is named in the same sentence as 19 diseases in open-access papers, as found by Europe PMC text mining. Sharing a sentence is not in itself a finding about the gene and the disease. The quoted sentences say what the papers report.
colorectal cancer (4 papers, 2020 to 2024). A primary or metastatic malignant neoplasm that affects the colon or rectum. "FKBP3 was reported to be closely associated with colorectal cancer and NSCLC." (PMID 36675710, 2022). "In colorectal cancer, silencing FKBP3 has been found to attenuate oxaliplatin resistance by regulation of the phosphatase and tensin homolog (PTEN)/AKT axis." (PMID 35087512, 2021). "The combination of FKBP3 and HDAC2 was related to oxaliplatin resistance in colorectal cancer via the PTEN/AKT pathway." (PMID 36675710, 2022).
lung adenocarcinoma (4 papers, 2021 to 2024). A carcinoma that arises from the lung and is characterized by the presence of malignant glandular epithelial cells. "In the present study, we explored the expression, clinical significance and the molecular mechanism of FK506 binding protein 3 (FKBP3) in the progression of lung adenocarcinoma (LUAD)." (PMID 38941396, 2024). "High level of FKBP3 is related to poor survival in lung adenocarcinoma (LUAD) patients." (PMID 37987202, 2024). "In order to verify the clinical value of the model, we finally examined the expression of FERMT2, FKBP3, SMAD9, GATA2 and ITIH4 in 30 lung adenocarcinoma tissues by immunohistochemistry, considering the availability of antibodies." (PMID 33648465, 2021). "The expression of the 6 key genes (FKBP3, GPI, LOXL2, IL22RA1, GPR37, has-miR-148a-3p) in lung adenocarcinoma patients with different tumor stages, T stages, N stages and M stages." (PMID 34040139, 2021).
breast carcinoma (3 papers, 2022 to 2025). "Downregulation of FKBP3 suppressed breast cancer, and FKBP3 expression was associated with poor survival in LUAD." (PMID 36675710, 2022). "Knockdown of FKBP3 restrained proliferation and invasion of breast cancer cells, and induced apoptosis of breast cancer." (PMID 37987202, 2024). "Melatonin regulates breast cancer progression through the lnc010561/miR-30/FKBP3 axis." (PMID 40756978, 2025). "Melatonin coordinates lncRNA to inhibit breast cancer development, and FK506-binding protein (FKBP3) and lnc010561 act as competing endogenous RNAs (ceRNAs) for the tumor suppressor mir-30, which regulates breast cancer development because of the significant downregulation of FKBP3 by melatonin." (PMID 40756978, 2025).
lung carcinoma (2 papers, 2021 to 2022). "FERMT2 together with FKBP3, SMAD9, GATA2, and ITIH4 was constructed as a prognostic signature of lung cancer based on the differential expression of immune genes." (PMID 36253873, 2022). "FKBP3 which is a member of FK506-binding proteins, could promote proliferation of lung cancer cells through regulating Sp1/HDAC2/p27, we assumed that its immunoregulation effects could be related to HDAC2." (PMID 33648465, 2021).
lymphoma (2 papers, 2015 to 2024). A malignant (clonal) proliferation of B- lymphocytes or T- lymphocytes which involves the lymph nodes, bone marrow and/or extranodal sites. "Previous studies showed increased expression of FKBP3 in lymphoma‐related cells." (PMID 37987202, 2024).
glioma (1 paper, 2021). A benign or malignant brain and spinal cord tumor that arises from glial cells (astrocytes, oligodendrocytes, ependymal cells). "In the signature, HDAC1 (HR:1.4938) and RBL1 (HR:1.7148) were deemed a hazard, while RUNX1T1 (HR:0.7349), FKBP3 (HR:0.6382), and PHF21A (HR:0.4956) promoted survival possibilities for glioma patients." (PMID 34540896, 2021). "Though the research on RUNX1T1, FKBP3, and PH21A in glioma was definite, the signature was annotated as “chromatin binding” by the functional enrichment analysis." (PMID 34540896, 2021).
HIV-1 infection (1 paper, 2021). The type species of lentivirus and the etiologic agent of acquired immunodeficiency syndrome (AIDS). "We next investigated how FKBP3 is induced during HIV-1 infection." (PMID 34281390, 2021). "Importantly, when HIV-1 infected the primary CD4+ T lymphocytes, the expression level of FKBP3 in these cells increased significantly, suggesting a possible involvement in the immune response of CD4+ T lymphocytes to HIV-1 infection." (PMID 34281390, 2021).
latent infection (1 paper, 2021). "To directly test whether FKBP3 promotes HIV-1 latency in primary human CD4+ T lymphocytes, we established a primary HIV-1 latent infection model (primary CD4+ T lymphocyte cells from three donors)." (PMID 34281390, 2021).
scleroderma (1 paper, 2013). Scleroderma is a rare autoimmune connective tissue disorder characterized by abnormal hardening of the skin and, sometimes, other organs. "To verify that this interaction is not cell type specific we repeated FKBP3/LARP6 pull downs in scleroderma skin fibroblasts with the same result (data not shown)." (PMID 23755290, 2013).
tumor (7 papers, 2021 to 2025). "Mechanically, FKBP3 promoted the tumor progression by regulating the ferroptosis and inhibited immune infiltration in LUAD progression." (PMID 38941396, 2024). "In three datasets, transcriptional levels of FKBP3 in tumor tissues were higher than those in normal samples." (PMID 36675710, 2022). "Related to HDAC class I signaling, FK506 Binding Protein 3 (FKBP3) regulated HDAC2 expression contributing to the drug resistance in tumor cells." (PMID 34540896, 2021). "As we known, Th2 response was crucial for pro-tumorigenic effects and promoting tumor progression, suggesting that FKBP3 might promote the tumor escape in the progression of cancers." (PMID 38941396, 2024). "All these results revealed that FKBP3 facilitated the growth of tumour in vivo." (PMID 37987202, 2024). "Thus, FKBP3 possessed the tumor promotion role might be involving in regulating ferroptosis and immune infiltration in LUAD progression." (PMID 38941396, 2024). "However, knockdown of FKBP3 treatment significantly reduced tumour volume (p < 0.01)." (PMID 37987202, 2024). "It indicated that FKBP3 may contribute to tumour metastasis." (PMID 37987202, 2024). "Our study demonstrated that FKBP3 aggravated the proliferation and stemness of DLBCL cells, and tumour growth in a xenograft mouse model." (PMID 37987202, 2024). "The heat map showed that the expression of DEGs in which FKBP3 and PARK7 were highly expressed in the tumour." (PMID 37987202, 2024). "Our results indicated that FKBP3 and PARK7 increased the stemness of DLBCL cells accordingly promoting tumour growth, and they were positively correlated." (PMID 37987202, 2024). "Our results demonstrated that FKBP3 was conducive to the malignant phenotype and stemness of DLBCL, and promoted the tumour growth in a xenograft mouse model." (PMID 37987202, 2024).
cancer (5 papers, 2021 to 2024). A tumor composed of atypical neoplastic, often pleomorphic cells that invade other tissues. "FK506‐binding protein 3 (FKBP3) contributes to the progression of various cancers and is highly expressed in DLBCL, but the role of FKBP3 in DLBCL and its mechanism are not clear." (PMID 37987202, 2024). "Previous studies suggested that FKBP3 plays a specific role in the regulation of protein ubiquitination, which in turn affects cancer progression." (PMID 37987202, 2024). "FOXO3 has cancer suppressive properties, while FKBP3 is carcinogenic." (PMID 37987202, 2024). "Previous studies determined that FKBP3 is a crucial oncogene in distinct cancers." (PMID 36675710, 2022).
cardiac disease (1 paper, 2024). "Regarding the miRNA–mRNA pairs, miR-125a-5p/NIPAL4, miR-135a-5p/ZNF385B, miR-140-3p/FKBP3, miR-140-3p/SKP1 and miR-140-3p/NDUFA4, very little or nothing is known about the function of these genes in cardiac disease." (PMID 39200271, 2024).
infection (1 paper, 2021). The state of being infected such as from the introduction of a foreign agent such as serum, vaccine, antigenic substance or organism. "The increased expression level of FKBP3 during establishment of the primary latent model inspired us to explore the role of FKBP3 in HIV-1 during the acute infection period." (PMID 34281390, 2021). "Therefore, during the acute infection period, cells expressed FKBP3 at a high level as an anti-HIV-1 response mechanism." (PMID 34281390, 2021). "Therefore, we considered whether the change in FKBP3 expression during the acute infection by HIV-1 is also regulated by IFN." (PMID 34281390, 2021). "In addition, FKBP3 could be induced by IFN-β and IFN-γ during the acute infection period, thereby inhibiting HIV-1 transcription and replication." (PMID 34281390, 2021).
FKBP3 also shares sentences with these, for which no sentence is quoted: aneuploidy (1 paper); B‐cell lymphomas (1); diffuse large B-cell lymphoma (1); infectious disease (1); lymph node metastasis (1); viral infection (1).